GLRX (glutaredoxin)
Diseases named in the same sentence as GLRX in open-access papers (continued):
Sharing a sentence is not in itself a finding about the gene and the disease.
Menkes disease (1 paper, 2011). A usually severe multisystemic disorder of copper metabolism, characterized by progressive neurodegeneration and marked connective tissue anomalies as well as typical sparse abnormal steely hair. "Glutaredoxin (thioltransferase), or GLRX, regulates the activity of the copper-transporting P-type ATPases ATP7A and ATP7B that are involved in Menkes disease (OMIM: #309400) and Wilson disease (OMIM: #277900), respectively." (PMID 21858011, 2011).
necrotizing enterocolitis (1 paper, 2024). Necrotizing enterocolitis (NEC) is a devastating disease that affects mostly the intestine of premature infants. "Zhang and colleagues explored the role of glutaredoxin-1 (Grx1) in necrotizing enterocolitis (NEC)." (PMID 38496303, 2024).
Nephropathy (1 paper, 2024). A nonspecific term referring to disease or damage of the kidneys. "The search term “(glutaredoxin* OR grx OR glrx OR thioltransferase) AND (diabetes OR islet* OR “beta cell*” OR pancreatic OR pancreas OR neuropathy OR nephropathy OR retinopathy OR “kidney disease”)” yielded a total of 108 primary articles." (PMID 38377787, 2024).
osteosarcoma (1 paper, 2021). A usually aggressive malignant bone-forming mesenchymal neoplasm, predominantly affecting adolescents and young adults.
pancreatic carcinoma (1 paper, 2014). "Glutaredoxin (GLRX) protects cells from oxidative stress and serves as a potential marker of malignancy in pancreatic carcinoma." (PMID 24548329, 2014).
infection (20 papers, 2012 to 2025). The state of being infected such as from the introduction of a foreign agent such as serum, vaccine, antigenic substance or organism. "During infection of blast pathogen on resistant and susceptible cultivars, primary response leads to respiratory burst that includes redox state genes like glutathione, glutaredoxin, thioredoxin, redoxin glutathione S-transferases and peroxidase." (PMID 33672641, 2021). "Cluster II, including genes downregulated after infection, dominated (57.14%); among this cluster are genes encoding 3 SOD, 1 CAT, 12 peroxidase, 2 glutaredoxin, 1 peroxiredoxin, and 5 thioredoxin." (PMID 35616396, 2022). "The mutant showed severely reduced transcription levels of genes related to glutaredoxin and thioredoxin in L. theobroame under oxidative stress or during infection, indicating an attenuated capacity for reactive oxygen species (ROS) detoxification." (PMID 34630367, 2021). "During infection, the transcript levels of genes in glutaredoxin and thioredoxin systems were significantly downregulated in the ΔLtap1 mutant." (PMID 34630367, 2021). "We found that LtAP1 was a key regulator of oxidative stress response, acting in activating fungal glutaredoxin and thioredoxin systems, and suppressing plant defense responses during infection." (PMID 34630367, 2021). "Overexpression of genes for the antioxidant enzymes SOD, CAT, GPX, GST, glutaredoxin (Grx), thioredoxin (Trx), and protein disulfide isomerase (PDI) was detected following the infection of mosquito cells with dengue virus." (PMID 40476361, 2025). "Here, we report the roles of a tomato glutaredoxin (GRX), SlGRXC6, in the infection of Tomato yellow leaf curl virus (TYLCV), a single-component geminivirus." (PMID 34398921, 2021). "In particular, we observed that gonococci expressed high levels of trx1, msrAB, and glutaredoxin genes during infection in male subjects, in agreement with the large PMN influx that occurs during infection in symptomatic men." (PMID 29950382, 2018). "To date, the biological functions of Grx in responses to oxidative stresses and host infection in gram-positive bacteria have not been investigated, which thus prompted us to elucidate the roles of glutaredoxin in the foodborne pathogen L. monocytogenes." (PMID 31680614, 2019). "Two WRKY70-like genes, FaWRKY70-1 (M17H1EST) and FaWRKY70-2 (M12E12EST), and a glutaredoxin GRX480-like gene, FaGRX1 (M30F8EST), which have been described as essential components for SA-dependent defense activation, were detected in strawberry after infection." (PMID 27471515, 2016). "Upon infection with Sendai virus, IRF3 undergoes deglutathionylation by the cytoplasmic enzyme, glutaredoxin-1 (GRX-1); it becomes phosphorylated, homodimerizes, translocates to the nucleus, binds to target genes and activates transcription by interacting with CBP/p300 co-activators." (PMID 24141185, 2013). "C. auris orthologous genes of other antioxidant mechanisms like catalases (CAT1) or the glutathione/glutaredoxin (GSH, GPX, GST) system were not up-regulated during blood infection, while they are used by C. albicans and C. glabrata under oxidative stress conditions." (PMID 35142597, 2022).
cancer (19 papers, 2015 to 2024). A tumor composed of atypical neoplastic, often pleomorphic cells that invade other tissues. "Many types of cancer have been shown to be dependent on redox-regulating mechanisms, such as the glutaredoxin and thioredoxin systems, and are therefore vulnerable to changes and offer a promising anticancer target." (PMID 34456713, 2021). "Recent studies demonstrate that cancers are highly dependent on the antioxidant and redox regulating thioredoxin (Trx) and glutaredoxin systems." (PMID 32727562, 2020). "Glutaredoxin is central to cellular redox chemistry and regulates redox homeostasis and malignant progression of many cancers." (PMID 33329553, 2020). "Overexpression of glutaredoxin and thioredoxin in cancer cells may further perturb the mechanisms limiting production of ROS by OGDHC in normal cells." (PMID 32466567, 2020). "Therefore, targeting cancer vulnerability by inhibiting either the thioredoxin or glutaredoxin system could pave a way to more cancer-specific therapies." (PMID 32727562, 2020). "Among these genes, several AA‐specific methylated genes such as GLRX,39RASSF1,40CAVIN3,41IRAG1,42IFFO1,43 and GEFT44 have been investigated for their potential roles in human cancers including PCa." (PMID 39162297, 2024). "In particular, H2AFV, CEBPB, SEC61G, GLRX, and PSMA5 exhibited dramatically worse overall survival in multiple cancers, which was consistent with their high expression in a variety of cancer tissues." (PMID 37251379, 2023). "Therefore, to evade ROS-induced cell death, cancer cells have an aberrant metabolism that promotes some agents to scavenge ROS and repair ROS-induced damage with molecules like glutathione peroxidase, glutathione-S-transferase, glutaredoxin, thioredoxin, superoxide dismutase, and catalase." (PMID 33959633, 2021). "Early approaches aimed to promote antioxidant activity for anti-cancer effect targeted antioxidants and ROS-scavenging systems, such as superoxide dismutase (SOD), glutathione peroxidases, peroxidoxins, glutaredoxin, thioredoxin, catalase, and nuclear factor erythroid 2-related factor 2 (Nrf2)." (PMID 33707480, 2021). "In our data, GLRX was considered to regulate the cancer stem cell phenotype via non-canonical Wnt signaling pathways associated with RhoA and ABCG2 via Wnt5a and Wnt7b." (PMID 34794402, 2021). "Thus, such known features of cancer cells as increased glutathione and the up-regulated thiol-disulfide reductases thioredoxin and glutaredoxin, may promote the ROS production by OGDHC, requiring decreased levels of holo-OGDHC in cancer vs normal cells." (PMID 32466567, 2020).
tumor (18 papers, 2015 to 2025). "Studies have shown that GLRX is highly enriched in certain tumors and is closely associated with tumor immune processes." (PMID 40626180, 2025). "It is known that upregulated thioredoxin and glutaredoxin can be a cause of chemotherapy resistance in various tumour entities." (PMID 33750814, 2021). "We found that GLRX is associated with high tumor grade and malignant phenotypes." (PMID 33329553, 2020). "We observed that the majority of immune functions showed positive correlation with GLRX; only the term “T cell-mediated immune response to tumor cell (T cell response)” was found to be negatively correlated with GLRX." (PMID 33329553, 2020). "The expression of GLRX was closely related to the tumor immune process, immune checkpoints, and inflammatory factors with GLRX being specifically expressed in M0 macrophages." (PMID 33329553, 2020). "A heatmap of the 110 CpGs shows overall lower methylation of these CpGs in tumors compared to adjacent non-tumor tissues: the top five hypermethylated genes were GLRX, WNT9B, SEPT9, KIAA00284, and PPYR1, and the top five hypomethylated genes were KIAA0748, PAEP, PCDH15, PTPRN2, and DUSP27." (PMID 34635168, 2021). "The glutaredoxin system in the tumor microenvironment may contribute to the reduction of the disulfide-bridged FAM-UNO that we observed upon incubation with the tumor lysate." (PMID 29116108, 2017). "Therefore, tumor cells must require strong ROS-scavenging systems (such as HO-1, superoxide dismutase, catalase, peroxiredoxin, thioredoxin, glutaredoxin, and glutathione peroxidase) to eliminate ROS, in which the HO-1 antioxidant system plays an important role." (PMID 37765244, 2023).
cardiovascular diseases (3 papers, 2020 to 2023). "This review primarily concerns the role of GSylation and Glrxs, particularly glutaredoxin-1 (Glrx), in cardiovascular diseases and the potential of Glrx as therapeutic agents." (PMID 32948023, 2020).
neurodegenerative disease (3 papers, 2008 to 2022). A disorder of the central nervous system characterized by gradual and progressive loss of neural tissue and neurologic function. "Thus, regulation of reversible protein-SSG formation has become a central issue in inflammatory responses and neurodegenerative diseases, focusing attention on the enzyme glutaredoxin (Grx1)." (PMID 29155853, 2017).
retinopathy (3 papers, 2016 to 2024). "Another example is GLRX, which was significantly increased in both stages of retinopathy." (PMID 35692536, 2022).
GLRX also shares sentences with these, for which no sentence is quoted: lung fibrosis (6 papers); ischemia (5); myocardial infarction (5); liver cancer (3); sarcopenia (3); bacterial infection (2); chronic myeloid leukemia (2); coronary diseases (2); hepatocellular carcinoma (2); hyperlipidemia (2); lung disease (2); malaria (2); malignant melanoma (2); neuroblastoma (2); non-alcoholic fatty liver (2); Non-Alcoholic Steatohepatitis (2); viral infections (2); adenocarcinoma (1); age-related macular degeneration (1); amyotrophic lateral sclerosis (1); Anxiety (1); astrocytoma (1); bladder tumours (1); brain tumors (1); cardiac hypertrophy (1); cholestasis (1); chronic obstructive pulmonary disease (1); colon adenocarcinoma (1); colorectal adenocarcinoma (1); COVID-19 (1).
A further 35 diseases each share a sentence with GLRX in 1 paper.